MTOR (mechanistic target of rapamycin kinase)
Diseases named in the same sentence as MTOR in open-access papers (continued):
Sharing a sentence is not in itself a finding about the gene and the disease.
cancer (continued). "mTOR dysregulation promotes cancer cell proliferation, angiogenesis, metabolic reprogramming, and survival while suppressing autophagy and apoptosis." (PMID 40869090, 2025). "Background/Objectives: Targeting the PI3K/mTOR pathway is a promising strategy in cancer therapy, but its efficacy is often limited by apoptosis resistance." (PMID 41471338, 2025). "Alterations in upstream proteins, such as the epidermal growth factor receptor (EGFR), can activate the mTOR/Akt pathway, leading to increased cancer cell survival by inhibiting apoptosis." (PMID 40287470, 2025). "Amino acid sensing plays a crucial role in activating mTORC1, and targeting amino acid metabolism—either alone or in combination with mTOR inhibition—has recently been suggested as a promising strategy for cancer therapy." (PMID 40425534, 2025). "It inhibits the PI3K/Akt/mTOR pathway, which is pro-proliferative in cancer and can lead to pathological hypertrophy in the heart." (PMID 41226835, 2025). "Its antitumor effects are mediated by AMPK activation, mTOR inhibition, suppression of insulin-mediated gluconeogenesis, and improved insulin sensitivity, which reduce cancer-promoting metabolic conditions." (PMID 40450131, 2025). "Recent studies suggest that tilianin suppresses PI3K/Akt/mTOR signaling, reducing Akt and mTOR phosphorylation, which disrupts cancer cell proliferation and promotes autophagy under metabolic stress." (PMID 41254699, 2025). "The PI3K/AKT/mTOR signaling pathway is a crucial regulator of autophagy and significantly influences cancer progression." (PMID 40076496, 2025). "What’s more, recent clinical trials have explored the efficacy of combining PI3K/Akt/mTOR inhibitors with other therapeutic agents to improve pain management in cancer patients." (PMID 40579593, 2025). "mTOR is one of the key mechanisms used by cancer cells to enhance their growth capacity, driving a wide range of biological processes to support the metabolic transformation of tumors." (PMID 41219936, 2025). "The AMPK pathway is a known regulator of cancer growth and progression, inhibiting several other pro-cancer pathways including mToR, HIF-1α, β-catenin, and Yap-1." (PMID 39941833, 2025). "While NF-κB and NRF2 mitigate inflammation and oxidative stress, mTOR signaling ensures sufficient energy availability for cancer cell growth." (PMID 40789840, 2025). "SLC7A5 activates the Akt/mTOR pathway to immunosuppress the tumor microenvironment and enhance radioresistance of cancer." (PMID 40362545, 2025). "Mammalian target of rapamycin (mTOR) is a critical cellular signaling protein, and the mTOR pathway has been found to be overactivated in various types of cancers, promoting their growth and proliferation." (PMID 40299634, 2025). "Through its involvement in boosting fatty acid metabolism, PPARG finely tunes the activation of the PI3K/Akt/mTOR pathway, affecting both drug sensitivity and cancer cell growth." (PMID 40303293, 2025). "AKT can be activated by PDK1 and mTOR, and over-activation of AKT can cause proliferation and survival of cancer cells." (PMID 40374533, 2025). "In various cancers, serine metabolism, one-carbon (1C) metabolism, and mTOR signaling pathways show abnormal hyperactivation." (PMID 40265021, 2025). "DEPTOR, a naturally occurring inhibitor of mTOR, plays crucial roles in tumorigenesis and is frequently dysregulated in a variety of human cancers." (PMID 40169856, 2025). "Nonetheless, recent advances in molecular characterization and diagnostic tools in cancer are gradually leading to the development of combined treatment strategies, associating PI3K/Akt/mTOR inhibitors with therapies targeting compensatory signaling pathways." (PMID 40647529, 2025). "The study showed that reducing Ephexin1 levels made cancer cells more sensitive to mTOR-blocking drugs, suggesting a new way to enhance cancer treatment." (PMID 40855114, 2025).
cancer (continued). "For example, investigations in obese tissues and cancer cell lines show a positive correlation between O-GlcNAcylation and mTOR phosphorylation, while OGT inhibition in cortical neurons increases autophagy markers via mTOR inhibition." (PMID 41101503, 2025). "The activation of the PI3K/AKT/mTOR signaling pathway in cancer cells has been shown to promote cancer cell proliferation and invasion." (PMID 40422575, 2025). "Although these mTOR inhibitors have shown clinical efficacy in select cancers, their broader application as myeloid compartment therapeutics is limited." (PMID 40821795, 2025). "While the PI3K/AKT/mTOR axis is well-characterized in cancer metabolism and EMT, most studies focus on canonical isoforms like PIK3CA or PIK3CB." (PMID 41362647, 2025). "More specifically, both TNBC and HER2-enriched cancers showed a PIK3R4 (a regulatory subunit of PI3K complex), and the HER2 + cancers an MTOR-associated defects of metabolic changes." (PMID 40700427, 2025). "Further analyses demonstrated that apigenin’s modulation of ER signaling suppressed the activation of the PI3K/Akt/mTOR pathway—a key regulator of cancer cell survival, proliferation, and resistance to apoptosis." (PMID 40667502, 2025). "Nevertheless, extensive evidence in the literature indicates that metformin can activate AMPK and suppress mTOR activity in many cancer models, which is consistent with the enhanced apoptotic response observed in our study." (PMID 41463522, 2025). "Given the pivotal role of the PI3K/AKT/mTOR signaling pathway in cancer biology, inhibiting this pathway has become a key strategy in anti-cancer therapy." (PMID 40303931, 2025). "Numerous physiological and pathological processes, such as cancer, metabolic issues, and neurological illnesses, depend on the mTOR pathway." (PMID 40717210, 2025). "Research has demonstrated that PI3Ks and their downstream effectors, such as AKT and the mammalian target of rapamycin (mTOR), are critical regulators of glycolysis, cancer metabolism, and cancer cell proliferation." (PMID 40221501, 2025). "Polymeric nanoparticles containing dual inhibitors of PI3K and mTOR have shown promising outcomes in preclinical cancer models." (PMID 40076496, 2025). "Inhibition of PI3K/Akt/mTOR signaling is a current therapeutic focus, particularly in hormone-driven cancers such as breast and prostate cancer, where targeting this pathway can enhance the efficacy of existing chemotherapies and immunotherapies." (PMID 40851957, 2025). "β‐Hydroxy‐β‐methylbutyrate (HMB), a metabolite of l‐leucine, enhances muscle protein synthesis through mTOR activation and improves muscle mass and function in patients with cancer." (PMID 40810552, 2025). "The mTOR pathway, frequently hyperactivated various cancers, including BC, drives excessive cell proliferation and resistance to apoptosis." (PMID 40926349, 2025). "Currently, 2-hydroxyglutarate serves as an oncometabolite found in cancers like kidney, hematopoietic, and neurocrine cancer, in which its mutation promotes HIF-1 and mTOR signaling pathway alterations as well as DNA repair disruptions." (PMID 40422872, 2025). "Given the enhanced efficacy of mTOR inhibitors when Ephexin1 is downregulated, Ephexin1 represents a promising target for synthetic lethality strategies in mTOR-targeted cancer therapies." (PMID 40855114, 2025). "Both cancers show suppression of the PI3K/Akt/mTOR pathway, a critical pathway for cell survival and proliferation, by isorhamnetin, leading to tumor growth inhibition and enhanced cancer cell death." (PMID 40806510, 2025). "Cancer is often characterised by dysregulation of signalling pathways like Hh, Wnt, and mTOR, which drive uncontrolled cell proliferation and high mitotic rates." (PMID 40017656, 2025).
cancer (continued). "DUBs regulate key signaling pathways such as NF-κB, PI3K/Akt/mTOR, and MAPK, and are implicated in a wide range of diseases, including cancer, neurodegenerative disorders, cardiovascular conditions, inflammation, and developmental abnormalities." (PMID 41463377, 2025). "By blocking the PI3K/AKT/mTOR signalling pathway, which is necessary for cancer cell survival and proliferation, RA decreases tumour volume and increases apoptosis rates." (PMID 40427522, 2025). "USP15 stabilizes Lectin Galactoside-Binding Soluble 3 (LGALS3) by blocking its ubiquitin-proteasome system-mediated degradation, thereby activating the AKT/mTOR axis to promote cancer stemness, proliferation, and lenvatinib resistance." (PMID 41298358, 2025). "mTOR represents a major focus in clinical and pharmaceutical research because of the deregulation of mTOR pathway in numerous human diseases, including neurodegenerative disorders and cancer." (PMID 41469379, 2025). "Our data indicate that when mTOR signaling is activated in cancer cells within the TME, endothelial proliferation activity increases, driven by the upregulation of pro‐angiogenic factors such as vascular endothelial growth factor (VEGF) and IL‐8." (PMID 39805002, 2025). "IGF-1, along with insulin, activates the PI3K/AKT/mTOR pathway, promoting cell growth, proliferation, and survival while inhibiting apoptosis, which are key processes that support cancer cell development." (PMID 40566597, 2025). "Silica-coated quantum dot nanoparticles stimulate the PI3K/AKT/mTOR pathway, inhibiting autophagy in resistant cancer cells." (PMID 40076496, 2025). "Reducing the high level of MCL1 in tumors has been suggested as a mechanism of action of several anti-cancer agents targeting mTOR signaling." (PMID 41326406, 2025). "PTEN is among the most commonly inactivated or mutated tumor suppressor genes in human cancers, with approximately 70% of advanced PCa cases exhibiting PTEN loss or consequent hyperactivation of the PI3K/Akt/mTOR pathway." (PMID 41009024, 2025). "Inhibiting key survival proteins like Akt and mTOR is a promising cancer treatment strategy, as this pathway is often dysregulated in cancers, including lung cancer." (PMID 40287470, 2025). "Intracellular signaling molecules upstream of mTOR, such as PI3K, PTEN, Akt, Ras, and Raf, are frequently mutated across many cancer types." (PMID 41356921, 2025). "Dysregulation of the mTOR signalling pathway is common in various human diseases, including cancers." (PMID 39542458, 2025). "Our study reveals a novel function of the FA pathway in suppressing mTOR signaling and protein translation, with important implications for cancer biology and therapeutic intervention." (PMID 40805278, 2025). "More information regarding the function of PI3K/Akt/mTOR on cancer and immune system can be found in these reviews." (PMID 40740483, 2025). "Given mTORC1’s established role in cellular aging and metabolism, SAMTOR emerges as a key regulator linking methionine availability to mTOR signaling and cancer progression." (PMID 40427696, 2025). "GADD45G promotes cell differentiation through negative regulation of the phosphoinositide 3-kinase/AKT/mTOR (PI3K/AKT/mTOR) pathway, and, consequently, its downregulation leads to activation of this pathway to drive cancer." (PMID 40188944, 2025). "This inhibition of the PI3K/AKT/mTOR pathway suppresses the proliferation of the cancer cells as well as elevating their apoptosis." (PMID 40164682, 2025). "Resistance to mTOR inhibitors is common in cancer cells due to feedback activation of upstream PI3K kinase, furthering the rationale to combine inhibition of PI3K /mTOR with other targeted inhibitors to achieve a more durable blockade of mTOR signaling." (PMID 39779613, 2025).
cancer (continued). "Lapatinib (Lap) is an inhibitor that can target the tyrosine kinase domains of HER2 and suppress the phosphorylation and signaling of MAPK and Akt/mTOR oncogenic pathways, inhibiting cancer proliferation and leading to apoptosis." (PMID 40332401, 2025). "Often hyperactivated through mutations or loss of tumor suppressors such as PTEN, this pathway promotes cancer cell proliferation and survival by inhibiting apoptosis and activating mTOR, which drives protein synthesis and suppresses autophagy." (PMID 40740483, 2025). "Previous studies have shown that baicalein induces the expression of DDIT4 and IRF-1 (Interferon regulatory factor-1), leading to inhibition of mTOR signaling in other cancer types." (PMID 41303544, 2025). "DDX5, in contrast, is generally described to have a consistently oncogenic effect through its regulation of the Wnt, Notch, mammalian target of rapamycin (mTOR), and forkhead box O3a (FOXO3a) pathways all involved in cancer progression." (PMID 39620586, 2025). "Considering this, mTOR inhibitors are theoretically capable of suppressing cancer cell growth and proliferation." (PMID 41399412, 2025). "The PI3K/AKT/mTOR pathway plays a key role in AML pathogenesis by regulating cancer cell proliferation and survival." (PMID 40917720, 2025). "Autophagy has emerged as a key cellular process implicated in cancer drug resistance, often regulated by the PI3K/AKT/mTOR axis." (PMID 40740483, 2025). "The dysregulation of the PI3K/AKT/mTOR pathway contributes substantially to the development of cancer drug resistance." (PMID 40142329, 2025). "This review examines advancements in nanoparticle-mediated drug delivery that target the PI3K/AKT/mTOR pathway, emphasizing their contribution to improving precision and minimizing side effects in cancer therapy." (PMID 40076496, 2025). "Pertinent to previous research, CAFs exert tumor-promoting effects across various cancer types, with their activity linked to several signaling pathways, notably PI3K/AKT/mTOR, WNT, and MAPK." (PMID 40530702, 2025). "For example, they can suppress the “PI3K/mTOR” pathway, which usually impairs the cancer cells and results in decreased cell viability and growth." (PMID 39803273, 2025). "This review presents an overview of advancements in nanoparticle-based strategies for modulating PI3K/AKT/mTOR-mediated autophagy in cancer." (PMID 40076496, 2025). "It inhibits the PI3K/Akt/mTOR pathway, essential for cancer cell growth and survival, and induces the nuclear translocation of the FoxO1 protein, affecting various cellular processes." (PMID 40868211, 2025). "Prunin is a prospective therapeutic agent for cancer treatment since it directly targets essential components of the PI3K/Akt/mTOR pathway." (PMID 40141319, 2025). "The suppression of mTOR by the FMD not only limits the growth of cancer cells but also enhances their sensitivity to chemotherapy by reducing their ability to repair damage." (PMID 39940361, 2025). "The study highlights the importance of knowing and monitoring mTOR in cancer treatment throughout the discussion and investigates various methodologies and procedures used for this aim." (PMID 40717210, 2025). "In cancer cells, PIK3CA activating mutations or deletions are common, and Akt overexpression prevents apoptosis or sustained activation of mTOR, and drug resistance occurs." (PMID 41050074, 2025). "The PI3K/Akt/mTOR signaling pathway plays a critical role in the apoptosis and proliferation of various cancer cells." (PMID 40098623, 2025). "Akt not only regulates cancer cell proliferation via mTOR but also plays an important role in PPARγ signaling." (PMID 40507124, 2025). "As oncogenic signalling pathways like MAPK/ERK, PI3K/Akt/mTOR, and others were uncovered, the link between faulty ribosome function and cancer became more apparent." (PMID 40805230, 2025).
cancer (continued). "Clinical results with mTOR inhibitors in renal and other cancers illustrate both monotherapy limits and the need for biomarker-informed combinations." (PMID 41300706, 2025). "Researchers and physicians have been investigating mTOR inhibitors as potential cancer treatments for over three decades, based on preclinical experiments and observational data." (PMID 40299431, 2025). "Kyoto Encyclopedia of Genes and Genomes (KEGG) enrichment analysis indicates that dysregulated genes in PTC cell lines overexpressing hsa_circ_0007694 are enriched in mTOR and Wnt signaling, as well as cancer‐related pathways." (PMID 39901896, 2025). "Given the role of the mTOR pathway in maintaining dormancy, a characteristic of both quiescent stem cells and quiescent cancer stem cells (CSCs), it plays a central role in the emergence of latent cancer cells." (PMID 39940361, 2025). "Reduced THOC2 expression subsequently led to the inhibition of the PI3K/AKT/mTOR signaling pathway, a key axis in cancer cell survival and progression." (PMID 40740483, 2025). "It inhibits cell proliferation and increases apoptosis, cycle arrest via various signaling pathways like the NF-κB, Wnt/β-catenin and mTOR, which are crucial for cancer progression and development." (PMID 40315213, 2025). "Chronic inflammation and cancer are intricately linked, driven by common signaling pathways such as NF‐kB, STAT3, and mTOR, which regulate proinflammatory cytokine production, creating a self‐sustaining feedback loop." (PMID 40387308, 2025). "Particularly, KEGG enrichment analysis suggested several enriched metabolites, including those of the FoxO signaling pathway, glycosylphosphatidylinositol (GPI) synthesis, choline metabolism in cancer, and the mTOR signaling pathway." (PMID 40692872, 2025). "In the constructed pan-cancer drug–gene network, the top hub gene of the network was mTOR, which interacted with 45 drugs, followed by BCL2, STAT3, and EGFR." (PMID 40293950, 2025). "Hyperactivation of the PI3K/AKT/mTOR pathway leads to increased tumor growth and survival, contributing to the aggressive clinical behavior observed in these cancers." (PMID 40072110, 2025). "Many anti-cancer treatments, such as nutrient deprivation or mTOR inhibitors, induce autophagy, thus aiding cancer cells in escaping drug effects." (PMID 40936705, 2025). "Recent evidence suggests a reciprocal relationship between ECM remodelling and mTOR pathway activation in cancer." (PMID 40860666, 2025). "Rapamycin and phenformin blocked the mTOR signaling pathway, inducing cancer cell autophagy and apoptosis, respectively." (PMID 41041304, 2025). "Here, we explored the potential for repurposing mTOR inhibitors in non-cancer therapeutic applications as they have already undergone safety and tolerability evaluations and are ready for clinical use." (PMID 40299431, 2025). "Its mechanism of action is by depletion of amino acids asparagine and glutamine, cellular deep metabolic stress that results in cancer cell apoptosis by a variety of complex cellular processes (e.g., mTOR pathway, autophagy)." (PMID 41459545, 2025). "In cancer development, the PI3K-AKT-mTOR pathway is hyperactivated due to mutations in PI3K, AKT, or mTOR or loss of the tumour suppressor PTEN, contributing to uncontrolled growth and therapy resistance." (PMID 40563591, 2025). "The PI3K/Akt/mTOR signalling pathway has been proven to have therapeutic value in osteoarthritis, malignant tumours, and certain neurological conditions." (PMID 40421249, 2025). "As an AMPK activator and mTOR inhibitor, metformin exerts tumor‐suppressive effects by reducing cancer cell proliferation, enhancing apoptosis, and modulating metabolic signaling." (PMID 40387523, 2025). "The phosphatidylinositol 3-kinase/protein kinase B/mechanistic target of rapamycin (PI3K/AKT/mTOR) signaling pathway is a highly relevant pathway for many pathological conditions, including cancer progression." (PMID 40149274, 2025).